CXCL10 (C-X-C motif chemokine ligand 10)
Diseases named in the same sentence as CXCL10 in open-access papers (continued):
Sharing a sentence is not in itself a finding about the gene and the disease.
tumor (continued). "These two chemokines have been involved in the regulation of tumoural neovascularisation, CXCL10 being usually described as an inhibitor of angiogenesis, whereas CX3CL1 has pro-angiogenic effects." (PMID 32946040, 2020). "CXCL10 is generally seen as a pro-inflammatory chemokine, which is essential for the recruitment of Th1 lymphocytes to the tumor site." (PMID 32355275, 2020). "Seven cases showed elevated levels of CXCL10 expression, with 13%–17% of tumor cells showing positivity for CXCL10 mRNA." (PMID 33234602, 2020). "We found that regorafenib treatment alone at 10 mg/kg and 20 mg/kg increased protein levels of CXCL10 evaluated in whole tumor tissue lysate by western blot analysis as early as 6 hours after treatment." (PMID 33234602, 2020). "Elevated serum CXCL10 and increased expression of CXCL10 and CXCR3 in tumor cells have been associated with a poor prognosis and metastasis." (PMID 32245422, 2020). "Fewer of the tumor tissues show positive staining of CXCL10 and iNOS in the groups treated with saline (Ctrl) or Abraxane alone (Ci and iii)." (PMID 32071352, 2020). "Regorafenib treatment increased the transcription and protein expression of CXCL10—a ligand for CXCR3 expressed on tumor-infiltrating lymphocytes—in murine HCC and in blood of patients with HCC." (PMID 33234602, 2020). "Several studies showed that CXCL9 and CXCL10, particularly CXCL10 produced by tumor or host cells can recruit CXCR3+ tumor-infiltrating CD4+ T cells, CD8+ T cells and NK cells that are associated with tumor suppression." (PMID 32547545, 2020). "Among the most bioactive IFN-I-induced genes, the chemokine (C-X-C motif) ligand 10 (CXCL10) functions as an important chemotactic factor and recruits immune members that selectively attack the tumor." (PMID 32340275, 2020). "CXCR3 is a chemotactic receptor on activated T cells, which binds CXCL10 released by tumor cells and by intratumoral activated DCs, following autocrine and paracrine stimulation by type-1 IFNs." (PMID 33281620, 2020). "The log2-fold change in expression of CXCL10 in DLBCL relative to that in paired normal tissues was significantly greater than that in any other type of tumor vs. normal." (PMID 33240622, 2020). "Neutralization of CD4, CD8, CXCL9, and CXCL10 abrogated the anti-tumor activity of combined therapy." (PMID 33167311, 2020). "The CXCR3 receptor and its cognate ligands, CXCL9, CXCL10, and CXCL11, which mainly secreted from tumor cells, have been implicated in recruiting CD8+ T cells to stroma." (PMID 32503584, 2020). "The expression levels of CXCL9, CXCL10, CXCL11, CXCL12, and CXCL14 were associated with various tumor stages in HNSCC." (PMID 33489879, 2020). "Tregs reduce endothelial CXCL10 production and inhibit T-cell migration into tumours, and CXCR3-mediated signalling is crucial for lymphocyte accumulation in intestinal tumours." (PMID 32680511, 2020). "Concomitantly, the production of the chemokines CXCL9 and CXCL10 by tumor-localized myeloid cells, including cDC1, was boosted by hetIL-15 in an IFN-γ-dependent manner." (PMID 32461349, 2020). "Since both CCL5 and CXCL10 attract CD8+ T cells into tumor sites, we next analyzed the effect of CD8 on the survival of patients from TCGA datasets." (PMID 31221150, 2019). "Another promising approach to elevate chemokine levels within the tumor is nanoparticle delivery as demonstrated by CXCL10-loaded folate-modified chitosan nanoparticles that showed anti-tumor activity." (PMID 30873179, 2019). "FIP200 deletion induced an anti-tumor immune response mediated by CD8+ and CD4+ T cell infiltration to the tumor site, mediated by IFNγ and chemokine secretion (CXCL9, CXCL10, CXCL11) by autophagy-deficient tumor cells." (PMID 31554173, 2019). "IL-17 signaling also inhibits the production of T cell attracting chemokines CXCL9 and CXCL10 by tumor cells." (PMID 31775909, 2019).
tumor (continued). "Intraperitoneal injection of bexarotene significantly decreased expressions of CCL22, CXCL5, CXCL10, and p19 in the tumor microenvironment." (PMID 31616630, 2019). "CCL2 and CXCL10, showed higher relative mRNA expression levels in tumors than in normal lamina propria of tumor bearing Apc1638N/+ mice correlating with the recruitment of myeloid cells and T lymphocytes into the tumors." (PMID 31681563, 2019). "CXCL9 and CXCL10 expression was decreased by adenosine signaling as metastatic melanoma developed in the lungs indicative of the ability of the tumor to suppress the chemokines responsible for attracting the CD8+ T cells." (PMID 30899263, 2019). "We showed that, in tumor lesions, the local expression of PD-L1 positively associates with the expression of CD8, CCL5, CXCL10, and also IFN response signature from the TCGA datasets." (PMID 31221150, 2019). "Intraperitoneal administration of bexarotene significantly decreased expressions of CCL22, CXCL5, CXCL10, IL-4, and p19 mRNA in the tumor microenvironment." (PMID 31616630, 2019). "Type 1 IFNs stimulate secretion of IP-10 (CXCL10) which is a critical chemokine to recruit effector T cells to the tumor microenvironment and IP-10 knockout mice exhibit a phenotype with compromised effector T cell generation and trafficking." (PMID 31393905, 2019). "IP-10, also known as CXCL10, is a chemoattractant for NK cells, and can activate NK cells leading to the lysis of tumor cells." (PMID 31105699, 2019). "After blockade of IL-4, the down-regulation of M1-associated cytokines (CXCL10, CD86, and IL-12) was observed as compared to cryo-thermal eosinophils + tumour-bearing macrophage group." (PMID 31519961, 2019). "Tumor cDC1 production of CXCL9 and CXCL10 can recruit activated T- cells to the TME where local cDC1 re-stimulation of T-cells support anti-tumor activity." (PMID 31402908, 2019). "Our qRT-PCR analysis demonstrated significant up-regulation of three tumor-promoting cytokines, Cxcl10, Ccl20, and Tnf and down-regulation of the tumor inhibitory cytokine Il24 in the MDA-F471 spheres relative to parental cells." (PMID 31001473, 2019). "In vivo, the interferon-γ (IFN) and IFN-induced chemokines CXCL9 (MIG) and CXCL10 (IP-10) showed increased expression in the tumor cells during salmonella treatment." (PMID 31598148, 2019). "On the other hand, other reports showed that chemokine ligands including CXCL9 and CXCL10 have potential angiostatic and anti-tumor activities." (PMID 31620367, 2019). "The high amount of CXCL10 detected in the urine seven days after the instillations denotes a persistent production that occurs in the tumor environment, as a consequence of the BCG treatment." (PMID 31277459, 2019). "CXCl10, also called IP10, stimulates the release of other chemokines, tumor progression, and metastasis via CRXR3 and activation of NF-κB signaling pathway." (PMID 31398937, 2019). "The authors thus demonstrated the existence of clusters of CXCL10-producing cells and their correlation with the presence of T cells in the tumor microenvironment." (PMID 31366174, 2019). "IP-10 (also known as CXCL10) was found to be enriched in the tumor (835.9 ± 210 pg/ml) compared to the adjacent healthy tissue (188.1 ± 100 pg/ml)." (PMID 31105699, 2019). "P8, who also had tumor progression, also had a very low CXCL10 concentration in the urine samples after the first cycle of instillations." (PMID 31277459, 2019). "In murine CD8+ T-cells, STAT3 has been shown to inhibit both IFN-γ-mediated CXCL10 production by myeloid cells and CD8+ T-cells CXCR3 expression (the receptor of CXCL10), blocking the migration of these cells to the tumor site." (PMID 31480382, 2019). "In our study, we also showed that IFN-I signature genes were closely associated with T cell infiltration including T cell marker CD8 and chemokines CCL5 and CXCL10 recruiting T cells to tumor sites." (PMID 31221150, 2019).
tumor (continued). "M1 macrophages also express higher levels of Nos2, Cxcl10, and Irf7 and expression of each of these genes increased in the injected tumor in response to combination treatment." (PMID 31921384, 2019). "The chemokine CXCL10 secreted by monocytes, endothelial cells, and fibroblasts has a lethal effect upon tumor cells." (PMID 31477121, 2019). "We further demonstrate that depletion of GBE1 can upregulate CCL5 and CXCL10 expression through STING signaling to activate IFN-I pathway, potentiate T cell infiltration, and cause induced expression of PD-L1 on tumor cells simultaneously." (PMID 31221150, 2019). "EZH2-mediated H3K27me3 and DNMT1-mediated DNA methylation repress the tumor production of T helper 1 (Th1)-type chemokines CXCL9 and CXCL10, and subsequently determine effector T-cell trafficking to the tumor microenvironment." (PMID 29556394, 2018). "Apart from mediating recruitment of protective immune cells, CXCL10 has been shown to reduce tumor progression independently of CXCR3." (PMID 29671006, 2018). "Radiation also induces the secretion of IFNγ and CXCL-10 in a melanoma mouse model, effecting the infiltration of CTLs, correlating with the inhibition of tumor growth and improved survival in mice." (PMID 30487462, 2018). "Macrophages, an important regulator of tumor progression, are known to produce CXCL10, and our data show that they do it to approximately the same extent as blood vessel endothelial cells but that macrophage CXCL10-production is unaffected by Treg depletion." (PMID 29671006, 2018). "CXCL10 is one of the interferon-stimulated chemokines that promotes infiltration of immune cells into the tumor microenvironment." (PMID 30080846, 2018). "Doxorubicin treated tumours showed significantly higher expression of Cxcl10, Cd274, Isg15, Psmb9 and Calr." (PMID 30400822, 2018). "While it has been established that type I interferons can enhance CXCL10 expression, the source of the interferon in the tumor environment was less clear." (PMID 30320116, 2018). "In contrast, tumor suppressive mediators made up most inversely correlated genes, e.g. CXCL10, CXCL11, IL15, TNFSF10/TRAIL, and TNFSF14/LIGHT." (PMID 29141914, 2018). "Proof-of-concept in a mouse model showed that the Sitagliptin-mediated DPP4 inhibition enhanced the tumor rejection by preserving the agonist form of CXCL10 and increasing the trafficking into the tumor by the CXCR3 expressing lymphocytes." (PMID 30026741, 2018). "In another study, VEGF was shown to be a negative regulator of transcription factor NFκB and the resultant decrease in tumor CXCL10 and 11, as a mechanism obstructing tumor T cell infiltration." (PMID 30126117, 2018). "The histological verification experiment showed differential expressions of the two main target genes GDF5 and CXCL10 between EBVaGC and non-tumor tissues as well as EBVnGC." (PMID 30258285, 2018). "It was shown that CXCL10, being secreted within the tumor, attenuates the process of new vessels formation and leads to reduced tumor growth in non-small cell lung cancer." (PMID 29977225, 2018). "It has been demonstrated in various cancers that the tumour microenvironment expresses CXCL10 (IP-10), which leads to Th1-specific recruitment to the site mediated by the CXCL10 receptor CXCR3 expressed on Th1 cells." (PMID 30075815, 2018). "Endothelial cells in human specimen were able to produce CXCL9 and CXCL10 in both unaffected tissue and tumor, confirming an endothelial origin of these chemokines in both species." (PMID 29671006, 2018). "Consistent with our in vitro experiments, analysis of NeuT tumor protein lysates showed that anti-MMP-9 treatment increases expression of CXCL10 and other T cell–stimulating factors, such as interleukin (IL)-12p70 and IL-18." (PMID 30500835, 2018). "Anti-tumor immunity within the TME can be supported by immune-stimulatory cytokines, such as CXCL9 and CXCL10, involved in the recruitment of immunological infiltrates at tumor site." (PMID 30581389, 2018).
tumor (continued). "Inhibition EZH2 in colorectal cancer cells augmented CXCL9 and CXCL10 expression to affect the infiltration of effector T cells in tumor." (PMID 29556394, 2018). "CXCR3 and CXCL10 immunoreactivity was mainly localized in epithelial cells within the tumor, but some minor staining was also observed in the inflammatory infiltrate." (PMID 29416784, 2018). "The expression levels of CXCL9 and CXCL10 also tend to be lower in the affected skin of patients with MF during the tumor stage than during the patch and plaque stages." (PMID 29915722, 2018). "CXCL10 is a potent monocyte and T-cell chemoattractant, promotes generation of effector T cells, and has been shown to exert tumor-suppressive functions in several cancer types." (PMID 29731994, 2018). "Most importantlysignificantly increased expression of Stat1(6.6-fold increase) and Cxcl10 (3.5-foldincrease) were noted in the tumours from STING agonist-treated mice." (PMID 30046165, 2018). "CXCL10 has been demonstrated to exert a positive effect on tumor cell invasion, migration, and survival in diverse human tumor cell lines." (PMID 30686982, 2018). "In the STING agonist-treated tumour-bearing mice, we foundsignificantly elevated levels of the cytokines, CXCL10, CCL5, IFN-γ, M-CSF, CXCL9and CXCL1 at early, mid and late time points in comparison to levels in plasmafrom vehicle-treated mice." (PMID 30046165, 2018). "These antitumor effects of CXCL10 are supposed to be, at least in part, related to promotion of immune activities against tumor cells." (PMID 29977225, 2018). "Migration of CD8+ T cells purified from spleens of ADAM28 KO or WT mice was assessed by modified Boyden Chamber assays using CXCL10 at different concentrations, CM from tumor cells or CM from CD8+ T cells used as chemoattractants." (PMID 30647853, 2018). "Our results suggest that persistent inflammation upregulates CXCL10 expression favoring tumor development via enhanced CXCR3A-CXCL10 signaling." (PMID 29416784, 2018). "Although macrophages are clearly important for tumor progression and also accumulate in the APCmin/+ tumors, this finding would indicate that Treg primarily reduce CXCL10 production by blood vessel endothelial cells to avoid a Th1 type response." (PMID 29671006, 2018). "Th1-derived IFN-γ is known to cause macrophage cytotoxicity to tumour cells and to stimulate macrophages to produce the angiostatic factors CXCL10/IP-10 and CXCL9/MIG." (PMID 29089667, 2017). "We evaluated the expression levels of CXCL10, the most relevant anti-antiangiogenic factor on tumor growth, since the main outcome is angiogenesis abrogation." (PMID 28376104, 2017). "In mice, inhibition of CD26 was found to protect CXCL10 from inactivation, resulting in enhanced T cell infiltration into the tumor tissue, thereby improving not only the natural antitumor immunity but also the response to existing immunotherapies." (PMID 29379506, 2017). "Our results suggest that the prostate possesses a unique environment that supports the local production of CXCL10, which is critical for the attraction of CXCR3+ effector cells to tumor-associated TLO." (PMID 28567040, 2017). "Our study represents the first report of Reolysin’s ability to induce CXCL10 and effectively disrupt tumor angiogenesis in vivo." (PMID 29156834, 2017). "THP1-macrophages exposure (24h) to lipopolysaccharide (LPS) polarizes them towards anti-tumor M1-macrophages, as detected by the increased expression of the M1-macrophage biomarkers; IL-12 and CXCL10 in them (see RT/PCR analysis, upper)." (PMID 29262555, 2017). "CXCL10 has been reported to be a potent inhibitor of angiogenesis, tumor cell proliferation, and metastasis." (PMID 29156834, 2017). "Among these, CXCL9 and CXCL10 stand out as their tumor expression correlates with prolonged disease-free survival of patients with colorectal carcinoma and other cancers." (PMID 28986561, 2017).
tumor (continued). "Together, these results show that tumor angiogenesis is regulated by nuclear Ca2+ likely through an increase in CXCL10 expression and secretion." (PMID 28376104, 2017). "IL-12p70 induced IFN-γ production, in turn, induces synthesis of the chemokine CXCL10 (IP-10; 10kD interferon γ-induced protein), which was the only cytokine that increased in multiparous mice in response to tumor induction." (PMID 28966800, 2017). "In agreement with our related in vitro assays, immunohistochemical analysis of tumor sections revealed a significant increase in CXCL10 expression in Reolysin exposed tumors, which was further augmented by the addition of temsirolimus." (PMID 29156834, 2017). "Consistent with previous reports, CXCL10+ epithelial cells were detected in a few tumor locations in PIN specimens." (PMID 28567040, 2017). "CXCL10 binds to CXCR3 receptor to promote tumor growth, migration, and invasion of cancer cells in several tumor types." (PMID 28611777, 2017). "Tumor size, multiplicity and incidence were reduced in Rag1-/- hosts implanted with CXCL10-expressing cells, as compared to control CT26 cells, but the differences did not attain significance." (PMID 29163806, 2017). "The data indicate that the effect of MSCs-Sirt1 in tumor suppression can be greatly blocked by CXCL10 inhibition." (PMID 27782173, 2016). "In order to further elucidate the role of CXCL10 in tumor inhibition, rabbit anti-murine CXCL10 was also applied to the tumor-bearing model." (PMID 27782173, 2016). "The secretion of CXCL10 and CXCL11 by neuroendocrine-like cells can recruit tumor-associated macrophages to infiltrate in tumor tissues." (PMID 27034164, 2016). "Dramatically, the tumor showed an increased weight and volume when rabbit anti-murine CXCL10 was additionally injected in tumor-bearing mice with MSCs-Sirt1 and 4T1 cells coinjection, compared with those under rabbit-serum injection." (PMID 27782173, 2016). "The chemokine CXCL10 is another factor with both tumor-promoting and anti-tumor effects, the latter largely through its immunogenic action." (PMID 27144453, 2016). "Noteworthy, it was recently reported that epigenetic modulation of CXCL9 and CXCL10 promoted tumor T cell infiltration and enhanced efficacy of PD-L1 blockade." (PMID 27343548, 2016). "On one hand, our data demonstrated an obvious increase of CXCL10 expression in serum level and mRNA level in vivo when the serum and tumors of tumor-bearing mice were harvested at the end of the experiment." (PMID 27782173, 2016). "We found CXCL9 and CXCL10 expressing on tumor cells and stromal cells, and CXCL11 expressing strongly on stromal cells and weakly on tumor cells." (PMID 26910919, 2016). "By contrast, local ionizing radiation coupled with vaccination increased CD8+ T cell infiltration that was associated with upregulation of CXCL10 and CCL5 chemokines in the tumor, but demonstrated modest inhibition of tumor growth." (PMID 27343548, 2016). "This disorganization is consistent with VEGF down-regulation and CXCL10 induction observed in cultured cells and tumor xenografts." (PMID 27329590, 2016). "A similar effect of EZH2 was observed in colorectal cancer, where targeting EZH2 in cancer cells augments the expression of CXCL9 and CXCL10 chemokines affecting the infiltration of the tumor by effector T cells." (PMID 27199994, 2016). "Depletion of CXCL10 dramatically decreased the number of tumor-infiltrating NK cells in tumor tissues of MSCs-Sirt1 treated mice." (PMID 27764779, 2016). "Activation of Cysteine-rich 61 protein (CCN1) also inhibited the oncolytic virus anti-tumor efficacy in glioblastoma through activation and infiltration of inflammatory TAMs and NK cells expressing IL-1β, IFNγ, CXCL10, and MCP-1/3." (PMID 28536380, 2016).